ACSM2B (acyl-CoA synthetase medium chain family member 2B)
Description:
Catalyzes the activation of fatty acids by CoA to produce an acyl-CoA, the first step in fatty acid metabolism. Capable of activating medium-chain fatty acids (e.g. butyric (C4) to decanoic (C10) acids), and certain carboxylate-containing xenobiotics, e.g. benzoate.
Synonyms: ACSM2; HYST1046; HXMA
Tractability: PROTAC: its protein half-life has been measured.
Gene: Protein-coding gene on chromosome 16 (20,536,226 to 20,576,442, reverse strand). Ensembl gene ENSG00000066813.
Subcellular location: Mitochondrion
Pathways (Reactome):
Metabolism: Conjugation of benzoate with glycine; Conjugation of phenylacetate with glutamine; Conjugation of salicylate with glycine
Drug ADME: Aspirin ADME
Gene Ontology:
Molecular function: benzoate-CoA ligase activity; decanoate-CoA ligase activity; medium-chain fatty acid-CoA ligase activity; protein binding; CoA-ligase activity; fatty acid ligase activity; fatty-acyl-CoA synthase activity; short-chain fatty acid-CoA ligase activity
Biological process: acyl-CoA metabolic process; fatty acid biosynthetic process; xenobiotic metabolic process
Cellular component: mitochondrion; mitochondrial matrix
Genetic constraint (gnomAD): Loss-of-function variants: 58 observed, 75.48 expected, observed/expected ratio (o/e) 0.77, 90% interval 0.62 to 0.96. The upper end of that interval is the gene's LOEUF score, 0.96, which puts it in group 4 of 6, group 1 being the genes least tolerant of losing a copy. Missense variants: 688 observed, 694.79 expected, observed/expected ratio (o/e) 0.99, 90% interval 0.93 to 1.05. Synonymous variants: 257 observed, 248.16 expected, observed/expected ratio (o/e) 1.04, 90% interval 0.94 to 1.15.
Homologues: Orthologues: chimpanzee ACSM2B (98% identical), rat Acsm2 (76% identical), mouse Acsm2 (75% identical), tropical clawed frog acss2.2 (26% identical), zebrafish acss2l (23% identical), Caenorhabditis elegans acs-2 (17% identical), Caenorhabditis elegans acs-1 (16% identical). Paralogues in human: ACSM2A (97% identical), ACSM4 (57% identical), ACSM1 (55% identical), ACSM3 (54% identical), ACSM5 (53% identical), ACSM6 (34% identical), ACSS1 (27% identical), ACSS2 (26% identical), ACSS3 (24% identical), AACS (22% identical), ACSF2 (20% identical), ACSF3 (18% identical), and 1 more.
Diseases named in the same sentence as ACSM2B in open-access papers:
ACSM2B is named in the same sentence as 5 diseases in open-access papers, as found by Europe PMC text mining. Sharing a sentence is not in itself a finding about the gene and the disease. The quoted sentences say what the papers report.
colonic adenomas (1 paper, 2023). "ElaC ribonuclease Z 2 (ELAC2) is primarily associated with prostate cancer, and MARCH6, along with ACSM2B, DEF8, DIS3L, and KCNA5 gene variants, have not been associated with colonic adenomas yet." (PMID 36765865, 2023).
gout (1 paper, 2020). A condition characterized by painful swelling of the joints, which is caused by deposition of urate crystals. "Of these, two loci from all gout types, rs76499759 of PIBF1 and rs9926388 of ACSM2B, and another two intergenic loci from normal type gout, rs146978188 of CD2-PTGFRN and rs548944057 of SLC28A3-NTRK2, were detected as novel loci." (PMID 32238385, 2020).
ACSM2B also shares sentences with these, for which no sentence is quoted: adenoma (1 paper); kidney disease (1); prostate carcinoma (1).